MEIS2 (Meis homeobox 2)
Description:
Involved in transcriptional regulation. Binds to HOX or PBX proteins to form dimers, or to a DNA-bound dimer of PBX and HOX proteins and thought to have a role in stabilization of the homeoprotein-DNA complex. Isoform 3 is required for the activity of a PDX1:PBX1b:MEIS2b complex in pancreatic acinar cells involved in the transcriptional activation of the ELA1 enhancer; the complex binds to the enhancer B element and cooperates with the transcription factor 1 complex (PTF1) bound to the enhancer A element; MEIS2 is not involved in complex DNA-binding. Probably in complex with PBX1, is involved in transcriptional regulation by KLF4. Isoform 3 and isoform 4 can bind to a EPHA8 promoter sequence containing the DNA motif 5'-CGGTCA-3'; in cooperation with a PBX protein (such as PBX2) is proposed to be involved in the transcriptional activation of EPHA8 in the developing midbrain. May be involved in regulation of myeloid differentiation. Can bind to the DNA sequence 5'-TGACAG-3'in the activator ACT sequence of the D(1A) dopamine receptor (DRD1) promoter and activate DRD1 transcription; isoform 5 cannot activate DRD1 transcription.
Synonyms: MRG1; HsT18361; CPCMR
Tractability: PROTAC: ubiquitination databases record sites on it; its protein half-life has been measured.
Gene: Protein-coding gene on chromosome 15 (36,889,204 to 37,101,307, reverse strand). Ensembl gene ENSG00000134138.
Subcellular location: Nucleus; Cytoplasm, perinuclear region
Subcellular location (Human Protein Atlas): Nucleoplasm; Cytosol
Gene Ontology:
Molecular function: DNA binding; DNA-binding transcription activator activity, RNA polymerase II-specific; protein binding; RNA polymerase II cis-regulatory region sequence-specific DNA binding; sequence-specific double-stranded DNA binding; DNA-binding transcription factor activity, RNA polymerase II-specific; transcription factor binding; sequence-specific DNA binding
Biological process: positive regulation of cardiac muscle myoblast proliferation; positive regulation of mitotic cell cycle; positive regulation of transcription by RNA polymerase II; animal organ morphogenesis; brain development; embryonic pattern specification; eye development; negative regulation of myeloid cell differentiation; negative regulation of transcription by RNA polymerase II; positive regulation of cell population proliferation; pancreas development; regulation of DNA-templated transcription; response to growth factor; response to mechanical stimulus
Cellular component: chromatin; nucleus; perinuclear region of cytoplasm
Genetic constraint (gnomAD): Loss-of-function variants: 9 observed, 61.61 expected, observed/expected ratio (o/e) 0.15, 90% interval 0.087 to 0.25. The upper end of that interval is the gene's LOEUF score, 0.25, which puts it in group 1 of 6, group 1 being the genes least tolerant of losing a copy. Missense variants: 427 observed, 669.96 expected, observed/expected ratio (o/e) 0.64, 90% interval 0.59 to 0.69. Synonymous variants: 221 observed, 242.57 expected, observed/expected ratio (o/e) 0.91, 90% interval 0.82 to 1.02.
Gene-disease validity (ClinGen):
ClinGen rates the evidence that MEIS2 causes each of these diseases.
syndromic intellectual disability (autosomal dominant): Definitive. A intellectual disability that is part of a larger syndrome.
Homologues: Orthologues: chimpanzee MEIS2 (100% identical), macaque MEIS2 (100% identical), guinea pig MEIS2 (99% identical), rabbit MEIS2 (99% identical), dog MEIS2 (99% identical), mouse Meis2 (99% identical), rat Meis2 (99% identical), pig MEIS2 (99% identical), tropical clawed frog meis2 (83% identical), zebrafish meis2a (78% identical), Drosophila melanogaster hth (52% identical), Caenorhabditis elegans unc-62 (43% identical), and 5 more. Paralogues in human: MEIS1 (69% identical), MEIS3 (55% identical), MEIS3P2 (51% identical), PKNOX2 (35% identical), PKNOX1 (32% identical), PBX1 (21% identical), PBX3 (20% identical), PBX2 (19% identical), PBX4 (17% identical), TGIF1 (14% identical), TGIF2 (11% identical), TGIF2LX (9% identical), and 1 more.
Diseases named in the same sentence as MEIS2 in open-access papers:
MEIS2 is named in the same sentence as 89 diseases in open-access papers, as found by Europe PMC text mining. Sharing a sentence is not in itself a finding about the gene and the disease. The quoted sentences say what the papers report.
prostate carcinoma (14 papers, 2013 to 2024). A carcinoma that arises from epithelial cells of the prostate gland. "It has been shown that MEIS1 and MEIS2 expression is associated with a more indolent phenotype of prostate cancer, with a lower risk of metastatic development." (PMID 36840946, 2023). "For example, the loss of MEIS2 affects the occurrence and progression of prostate cancer and can be used for targeted therapy or for monitoring the condition of a disease." (PMID 33975520, 2021). "Downregulation of MEIS2 in prostate cancer cells activates the signaling circuit and promotes CRPC development." (PMID 38711262, 2024). "A recent study revealed that targeting MEIS2 expression inhibits proliferation and invasion of prostate cancer cells." (PMID 39776641, 2024). "While, in prostate cancer, MEIS2 is an important component of a constitutive intrinsic inflammatory signaling circuit, that controls the constitutive NF‐κB activation in CRPC cells." (PMID 38711262, 2024). "circDHRS3 is a miRNA sponge for miR-421 which targets the expression of MEIS2 to inhibit the proliferation and invasion of the prostate cancer cell." (PMID 36840946, 2023). "The rescue assay results for the PC3 and Du145 cell lines demonstrated that circDHRS3 inhibits prostate cancer cell lines’ ability to proliferate and metastasize by modulating MEIS2 expression through the circDHRS3/miR-421/MEIS2 axis." (PMID 36840946, 2023). "Our study indicates that circDHRS3 inhibits prostate cancer cell proliferation and metastasis through the circDHRS3/miR-421/MEIS2 axis." (PMID 36840946, 2023). "Analyses of mRNA documented that PrECs and prostate cancer cell lines express multiple detectable MEIS2 transcript isoforms, albeit at low levels of expression." (PMID 32553107, 2020). "MEIS2 was identified in an array screening as one of the top 50 downregulated genes in prostate cancer." (PMID 29757984, 2018). "The rescue assay further indicated that circDHRS3 could regulate MEIS2 expression in prostate cancer by antagonizing miR-421." (PMID 36840946, 2023). "A literature survey revealed that MEIS2 is downregulated in metastatic sites of prostate cancer." (PMID 36840946, 2023). "Additionally, MEIS2 expression is decreased in poor-prognosis tumours and participates in the emergence of castration-resistant prostate cancer." (PMID 36840946, 2023). "We also found that the circDHRS3/miR-421/MEIS2 axis may play a role in the onset and progression of prostate cancer." (PMID 36840946, 2023). "We found that MEIS2 was down-regulated in prostate cancer samples." (PMID 36840946, 2023). "MiR-421 and MEIS2 are both correlated with prostate cancer and ADT resistance, but whether this axis influences ADT resistance remains unknown." (PMID 36840946, 2023). "We established PC3 and Du145 cell lines transfected with MEIS2 knockdown or overexpressed miR-421 to further uncover the relevance of the circDHRS3/miR-421/MEIS2 axis in regulating the proliferation, migration, and invasion of prostate cancer." (PMID 36840946, 2023). "In addition, studies have revealed the correlation between MEIS2 and the occurrence of prostate cancer, ovarian cancer, neuroblastoma and other diseases." (PMID 33975520, 2021). "Meis1 and Meis2 expression determine the aggressiveness of prostate cancer." (PMID 33402862, 2020). "In our study, knockdown MEIS2 expression may promote the invasion of prostate cancer." (PMID 36840946, 2023). "The circDHRS3/miR-431/MEIS2 axis could influence the occurrence and development of prostate cancer." (PMID 36840946, 2023). "However, MEIS2 is down-regulated in advanced prostate cancer." (PMID 31623651, 2019). "(B) Western blot analysis of endogenous MEIS1, MEIS2, and HOXB13 expression from common prostate cancer cell lines and primary Prostate Epithelial Cell (PrEC) culture." (PMID 32553107, 2020). "miRNA-204 is another key regulator in prostate cancer progression as it regulates several genes, like MEIS1 and MEIS2, as a result of protein complex dysregulation." (PMID 24391925, 2013).
prostate carcinoma (continued). "In prostate cancer, MEIS2 shows a negative role in the regulation of a constitutive intrinsic inflammatory signaling circuit that promotes castration‐resistant prostate cancer (CRPC) development." (PMID 38711262, 2024).
Intellectual disability (11 papers, 2015 to 2025). "In contrast, in females, DAS gene networks, including Ubap2l, Pik3cd, and Meis2, were primarily associated with neuritogenesis, neuronal development, and intellectual disability." (PMID 40790242, 2025). "The characteristic features of a heterozygous missense mutation in the MEIS2 gene locus or a 15q14 microdeletion are a triad of cleft palate, congenital heart defects, and intellectual disability, which is referred to as MEIS2 syndrome." (PMID 39776641, 2024). "A mutation of Meis2 that causes intellectual disability in humans was much less able to potentiate the DLX5-induced activation of these CREs." (PMID 38528203, 2024). "The phenotypic expression varies among individuals with genetic variants in MEIS2, ranging from cleft palate, heart malformations, severe intellectual disability and hypotonia to cleft palate and learning problems." (PMID 39639090, 2024). "It has been established that haploinsufficiency of the MEIS2 gene cause a syndromic form of OFCs, often presenting with cardiac defects, facial dysmorphism, as well as intellectual disability at a variable severity." (PMID 34930369, 2021). "MEIS2 deletions/mutations have been associated with cleft lip/palate, dysmorphic facial features, cardiac defects, as well as intellectual disability at a variable severity." (PMID 34930369, 2021). "Consistent with the function of Meis2 in mice, the patients carrying MEIS2 mutations present developmental abnormalities, including intellectual disability (ID), cleft palate, and defects in heart development." (PMID 30526668, 2018). "Meis2 has been associated with cardiac septal defects and cleft palate as well as intellectual disability." (PMID 26512644, 2015). "Intriguingly, several reports describe patients with Meis2 mutations who display disorders such as the cleft palate, septal defects in the heart or intellectual disabilities." (PMID 26545946, 2015). "Consistent with these phenotypes, heterozygous MEIS2 missense mutations or 15q14 microdeletion involving the MEIS2 gene locus are characterized by a triad of cleft palate, atrial or ventricular septal heart defects, and intellectual disability, known as MEIS2 syndrome." (PMID 38305737, 2024). "MEIS2 mutations, including genomic microdeletions and SNVs and indels, have been recently identified to cause syndromic phenotypes, including palatal defects, congenital cardiac defects, and intellectual disability at variable severity and penetrance." (PMID 34930369, 2021). "The transcription factor MEIS2 also plays a role in disorders such as cardiac defects and intellectual disability." (PMID 38347632, 2024). "Haplo-insufficiency of the MEIS2 in humans results in an autosomal dominant disease characterized by several congenital malformations, mild-to-severe intellectual disability with poor speech and delayed psychomotor development." (PMID 38528203, 2024). "Haploinsufficiency of MEIS2 with the pLI score of 1 is considered to be responsible for a syndromic phenotype with cleft palate, intellectual disability, heart defects, and dysmorphic features." (PMID 34930369, 2021). "Furthermore, research has shown a connection between the MEIS2 gene and neurodegenerative illnesses and intellectual disability." (PMID 39776641, 2024). "However, she did not exhibit intellectual disability, which further expands the spectrum of clinical phenotypes caused by the same MEIS2 gene mutation." (PMID 39776641, 2024).
neuroblastoma (11 papers, 2014 to 2024). Neuroblastoma (NB) is the most common solid, extracranial childhood tumor. "The overexpression of Meis1 and Meis2 in neuroblastoma cells is associated with increased tumor progression." (PMID 33402862, 2020). "In this study, we investigated the function of MEIS2 in neuroblastoma cells and the underlying molecular mechanism." (PMID 25210800, 2014). "The inhibition of Meis1 and Meis2 expression also causes apoptosis in neuroblastoma cells." (PMID 33402862, 2020). "Abnormal expression of MEIS2 significantly impacts neuroblastoma cell proliferation and tumorigenicity." (PMID 39776641, 2024). "MEIS2 is essential for neuroblastoma cell survival and up-regulation of MEIS2 is required for the growth of AML1-ETO-positive AML." (PMID 37621680, 2023). "And in human neuroblastoma cell lines, MEIS2 is of high expression, and it is the essential requirement for tumor cell proliferation and survival." (PMID 33975520, 2021). "Second, MEIS2 was previously reported as a key factor supporting neuroblastoma cell survival and established as a neuroblastoma-specific dependency factor by DEPMAP consortium screening." (PMID 34638267, 2021). "First, we identified MEIS2 as a putative key transcriptional driver during early neuroblastoma tumor formation." (PMID 34638267, 2021). "This analysis again highlighted our finding of MEIS2 as a putative key early dependency during murine TH-MYCN-driven neuroblastoma." (PMID 34638267, 2021). "Further in vivo functional analysis is warranted to unravel the precise role of MEIS2 during early neuroblastoma tumorigenesis." (PMID 34638267, 2021). "Most TALE subfamilies (including Meis1, Meis2, and Pbx2) are upregulated in a set of neuroblastoma cell lines, suggesting that the regulation of TALE transcription is functional in tumorigenesis." (PMID 33402862, 2020). "Meis1 and Meis2 were upregulated in parallel, only in neuroblastoma, gynecologic, and thymoma cancers." (PMID 33402862, 2020). "It has been reported that MEIS2 affects neuroblastoma proliferation and differentiation in opposing ways, depending on the relative expression of two of its alternative splice isoforms." (PMID 31623651, 2019). "In neuroblastoma, leukemia, and multiple myeloma, MEIS2 serves as an oncogene and, similarly seems to play an important role in tumor cell migration and invasion in bladder and colorectal cancer." (PMID 31640805, 2019). "Accumulating research suggests an oncogenic role for MEIS2 in the development of neuroblastoma, leukemia, bladder, prostate, and ovarian cancer." (PMID 31623651, 2019). "It has been shown that MEIS2 is essential for the survival and proliferation of neuroblastoma cell by transcriptional control of M-phase progression." (PMID 31623651, 2019). "It was shown that the depletion of Meis2 in neuroblastoma cells leads to M-phase arrest and mitotic catastrophe." (PMID 26512644, 2015). "Recently, an essential role of Meis2 in the transcriptional control of M-phase cell cycle progression was presented in neuroblastoma cells." (PMID 26512644, 2015). "Collectively, these findings indicate that high-level expression of MEIS2 is essential for the survival of neuroblastoma cells." (PMID 25210800, 2014). "Depletion of MEIS2 in neuroblastoma cells leads to M-phase arrest and mitotic catastrophe, whereas ectopic expression of MEIS2 markedly enhances neuroblastoma cell proliferation, anchorage-independent growth, and tumorigenicity." (PMID 25210800, 2014). "Consistent with previous reports, immunoblot analysis of a panel of 13 human neuroblastoma cell lines revealed that they all expressed significant levels of MEIS2 isoforms with apparent molecular weight of 46–60 kDa." (PMID 25210800, 2014). "Here, we show that MEIS2 is highly expressed in human neuroblastoma cell lines and is required for neuroblastoma cell survival and proliferation." (PMID 25210800, 2014).
neuroblastoma (continued). "Collectively, these findings suggest an oncogenic activity of MEIS2 in neuroblastoma pathogenesis and shed light on the molecular mechanism for the biological function of MEIS2 in development." (PMID 25210800, 2014). "A majority of FOXM1 target genes, including CDC25B, CHEK2, CENPA, CENPB, and CENPF, were significantly downregulated in neuroblastoma cells with MEIS2 depletion." (PMID 25210800, 2014). "In this report, we present evidence for an essential role of MEIS2, an important regulator of development, in the control of cell-cycle progression in neuroblastoma cells." (PMID 25210800, 2014). "Recent single-cell transcriptome analysis of the developing sympatho-adrenal lineage evidenced strong enriched MEIS2 expression in the population of sympathoblast cells that resemble the neuroblastoma cancer cell phenotype compared to chromaffin and Schwann cell precursor cells (left)." (PMID 34638267, 2021). "We could show that pharmacological MEIS2 inhibition negatively impacted on neuroblastoma cell confluence." (PMID 34638267, 2021). "We show that depletion of MEIS2 in neuroblastoma cells induces mitotic spindle aberrations, centrosome amplification, and M-phase arrest, leading to mitotic catastrophe, whereas ectopic MEIS2 expression enhances the proliferation and tumorigenicity of neuroblastoma cells." (PMID 25210800, 2014). "Thus, MEIS2 at its steady-state levels has an essential role in the transcriptional activation of key cell-cycle genes, at least in neuroblastoma cells." (PMID 25210800, 2014). "Importantly, FOXM1 depletion by shRNA significantly abolished the ability of MEIS2d to upregulate the expression of mitotic genes, demonstrating that FOXM1 is an essential mediator of MEIS2 action in neuroblastoma cells." (PMID 25210800, 2014). "Thus, FOXM1 depletion or inhibition in neuroblastoma cells fully recapitulated the phenotype of MEIS2 depletion at both molecular and cellular levels." (PMID 25210800, 2014). "It is known that cells with FOXM1 depletion display mitotic spindle defects, centrosome amplification, chromosome mis-segregation, failure of cytokinesis, and mitotic catastrophe, which are essentially the same phenotypes displayed by neuroblastoma cells with MEIS2 depletion." (PMID 25210800, 2014). "Similarly, MEIS2 has been shown to be essential for neuroblastoma cell survival and proliferation." (PMID 33402862, 2020). "Hence, an increased expression of Meis1 and Meis2 may be involved in the promotion of neuroblastoma formation; thus, they may act as oncogenes." (PMID 33402862, 2020). "In other cancers including neuroblastoma, high level expression of MEIS1 and MEIS2 genes was demonstrated, and defective MEIS1 cells showed impaired proliferation leading to cell death." (PMID 32819319, 2020). "Together, these data indicate that MEIS2 depletion induces predominantly non-apoptotic cell death in neuroblastoma cells." (PMID 25210800, 2014). "Notably, MEIS2 is a direct transcriptional regulator of FOXM1 and indirect regulator of DREAM expression, warranting further functional studies to further dissect the mechanistic role of MEIS2 during neuroblastoma tumor development." (PMID 34638267, 2021). "In order to gain further insight into the possible early role of Ascl1 and Meis2 in MYCN-driven tumor formation compared to the other core regulatory circuit members, we compared their time-resolved expression during murine TH-MYCN-driven neuroblastoma tumor development." (PMID 34638267, 2021).